AHR (aryl hydrocarbon receptor)
Diseases named in the same sentence as AHR in open-access papers (continued):
Sharing a sentence is not in itself a finding about the gene and the disease.
gastrointestinal disorders (2 papers, 2023 to 2024). "While current evidence suggests probiotics can positively influence health in both healthy individuals and populations with gastrointestinal disorders, additional research is required to elucidate the specific roles of AhR signaling in both human and animal models." (PMID 39517263, 2024). "Therefore, one could anticipate that individuals from the cohort with IDO/AhR activation would present with more gastrointestinal disorders." (PMID 38071324, 2023).
genetic disorder (2 papers, 2017 to 2020). "The goal of this study is to delineate the molecular basis of this newly discovered human genetic disorder associated with a rare AHR gene mutation." (PMID 33193710, 2020).
connective tissue disease (1 paper, 2020). "AhR signaling pathways may therefore be useful therapeutic targets for connective tissue disease-associated ILD." (PMID 32033616, 2020).
head and neck tumor (1 paper, 2018). "Furthermore, our group previously demonstrated that AHR antagonism attenuates aggressive phenotypes in head and neck tumor cell lines." (PMID 30501068, 2018).
peripheral neuropathies (1 paper, 2016). "Kyn is also a weak ligand for aryl hydrocarbon receptors (AhR) expressed by multiple cell types in CNS and non-CNS tissues and modulation of AhR signaling during IAV and MuLV infections may also contribute to peripheral neuropathies that drive increased pain sensitivity." (PMID 27168185, 2016).
AHR also shares sentences with these, for which no sentence is quoted: Allergy (14 papers); cystic fibrosis (5); bronchitis (4); end-stage renal disease (4); adult T-cell leukemia (3); astrocytoma (3); autoimmune encephalitis (3); helminth infection (3); hepatitis C (3); Hereditary breast cancer (3); malnutrition (3); neurotoxicity (3); sarcoma (3); actinic keratosis (2); acute coronary syndrome (2); AIDS (2); alcohol (2); ankylosing spondylitis (2); aspergillosis (2); bowel obstruction (2); cholestasis (2); colon adenoma (2); fibrosarcoma (2); gestational diabetes (2); hematologic cancer (2); hidradenitis suppurativa (2); Hydroureter (2); idiopathic pulmonary fibrosis (2); macular degeneration (2); obstructive sleep apnea (2).
A further 113 diseases each share a sentence with AHR in 2 papers or fewer.